IL6 (interleukin 6)
Diseases named in the same sentence as IL6 in open-access papers (continued):
Sharing a sentence is not in itself a finding about the gene and the disease.
infection (continued). "IL-6 expression was similar between Mda5-KO and NTC cells at 24 hours after infection, although Mda5 knockdown resulted in slightly elevated IL-6 RNA levels at 4 hours after infection." (PMID 37725440, 2023). "The inflammatory response of MIO-M1 cells to infection with Mon601 was characterized by elevated expression of tumour necrosis factor (TNF)-α, interleukin (IL)-1β, and IL-6 (p < 0.01) compared to uninfected control cells." (PMID 37515098, 2023). "The cell model and mouse model infection experiments indicated that TF1 decreased the adhesion ability and virulence of SC19, and reduced the production of IL-6, and TNF-α in infected mice." (PMID 37108608, 2023). "The cytokines IL-6, TNF-α, and MCP-1 showed significantly higher levels in the groups treated with LT-P EVs before the infection with LT-P compared to the untreated and uninfected groups." (PMID 38138117, 2023). "IL-6 and TNF-α are typical pleiotropic cytokines produced in response to tissue damage and infection." (PMID 37630849, 2023). "AMs play a central role in homeostasis, tissue remodeling and during pathogen infection and inflammation, and produce various cytokines such as TGF-β, IL-6, and type I interferons." (PMID 37781389, 2023). "The infection induced an enduring high inflammatory cytokine response in HLA-A11/DR1 mice after 72 h, including elevated TNF-α, IL-6, IFN-γ, and GRO-α levels compared to the WT mice." (PMID 38035330, 2023). "IL-6 induces the production of C-reactive protein (CRP) and procalcitonin (PCT), which are directly related to inflammatory diseases and the severity of infection." (PMID 37158301, 2023). "The administration of progesterone at day 1 and 2 post-infection decreased the expression of IFN-γ and IL-6 in the spleen of the infected pregnant mice, and the same happened with the serum levels of these cytokines." (PMID 38133333, 2023). "In one study, the expression of TNF-α, IL-6, and IL-1β in THP-1 cells was increased significantly within 48 h after infection, whereas secretion of the anti-inflammatory factor IL-10 was inhibited." (PMID 37841250, 2023). "Infection with these bacteria induced solid inflammatory responses and a substantial increase in the inflammatory cytokine release of TNF‐α, IL‐6, IL‐1β, and IL‐18 in macrophages derived from March5fl/fl mice." (PMID 37575012, 2023). "The early infection group had more patients with CD4+ T-cell counts < 300/μL (P = 0.005), as well as higher interleukin (IL)-6 (P < 0.001) and IL-8 (P = 0.013) levels." (PMID 37360336, 2023). "Infection with both ZIKV lineages was characterized by a more proinflammatory and chemotactic profile, mediated by high levels of IL-1β, IL-6, TNF-α, CCL-2, CCL-3, CCL-7, CXCL8, IP-10, and VEGF." (PMID 37227282, 2023). "Here, in the mild SFTSV-infected macaques, the levels of IL-6, MCP-1, and IP-10 were significantly increased during infection." (PMID 37033979, 2023). "The genotype VII virulent GD strain elevated IL-6 mRNA levels in the lung and Harderian gland of one-day-old SPF chickens at 48 h after infection." (PMID 37112843, 2023). "In line with the higher bacterial load at peak infection, on day 3 Calhm6−/− mice showed a higher inflammatory response in serum, with increased levels of pro‐inflammatory cytokines IFN‐γ and IL‐6, and lower levels of anti‐inflammatory IL‐10." (PMID 36861806, 2023). "In the recovery phase (D10), as the immune system and treatment brought the infection under control, WBC and levels of IL-6, CRP, hepcidin, and LCN2 substantially decreased compared to the acute phase of infection." (PMID 37932342, 2023). "By day 2 after infection, significant elevations in the levels of interleukin-1β (IL-1β), TNF-α, IL-6, IFN-γ, IFNα, IFNβ, CXCL1, CCL2, and CCL5 were detected in the airways of influenza virus–infected mice." (PMID 37683004, 2023). "CRP is increased in response to IL-6, IL-1β and TNF-α activation during infection and systemic inflammation." (PMID 35958594, 2022).
infection (continued). "DMF treatment after infection with HK‐MRSA, which is termed posttreatment, also suppressed the production of IL‐6 and TNF‐α." (PMID 36354099, 2022). "The levels of IL-6 and TNF-α in the model group were significantly increased on both day 4 and day 7 post-infection when compared with the control group." (PMID 36452894, 2022). "IL-6 and TNF-α were significantly elevated on day one after infection, and the expression trends of plasma cytokines in mice on days 1, 3, and 5 of the experiment were inconsistent and did not correspond completely to the elevated plasma levels of CyPA." (PMID 36569095, 2022). "As for the protein levels of cytokine profiles in the ileum, DON infection induced dramatic increases in the expression of ileal IL-1β, TNF-α and IL-6 proteins (p < 0.01)." (PMID 36139849, 2022). "denticola infections decreased IL-6, IL-1β, and CCL5/RANTES compared to single species infections with each of the bacterium in macrophage/epithelial cell co-culture model." (PMID 35203495, 2022). "At 24 h post infection, there was increased expression of TNF-α, IL-1β, IL-6, and IL-12 in the lungs of mice infected with the ΔEfb strain compared to those infected with the Newman and ΔEfb + Flag − Efb strains." (PMID 36123338, 2022). "In the primary infection, the mRNA levels of cytokines and chemokines including RANTES, IFN-α, MIP-1-α, IFN-γ, IL-6, IP-10, TNF-α, and IL-1-β were increased in the nasal mucosa and lung, except IL-1-β, which was not increased in the lung." (PMID 35893674, 2022). "Measures such as promastigote growth curves, macrophage infection profiles, inflammatory mediators’ production (TNF-α, IL-6 and NO) and serine proteases expression (subtilisins and OPB) showed heterogenic profiles of these clinical isolates." (PMID 35531337, 2022). "In the case of SARS-CoV-2, an increase in the concentration of inflammatory cytokines such as IL-1β, IL-2, IL-6, IL-7 and TNF-α comes to the fore, along with the rise in IL-4 and IL-10 concentrations in a later stage of infection." (PMID 36294388, 2022). "Another sign of rising infection can be a rise in specific infection laboratory factors, such as PCT, Interleukin 6, TNF alpha (tumour necrosis factor), and others." (PMID 36013534, 2022). "Incision infection after calcaneal fracture affects the clinical treatment effect, and serum IL-2, IL-6, and CRP levels increase in patients with postoperative incision infection after bone fracture." (PMID 36091601, 2022). "In terms of infection index, PCT decreased by 48.79% (p < 0.001) after 24 h of treatment, and IL-6 decreased by 81.80% (p < 0.001)." (PMID 36249210, 2022). "Specifically, infection of mice with murine CMV has been shown to increase levels of IL-12, INF-γ, TNF-α, and IL-6." (PMID 35458404, 2022). "In particular, IL-6 is a more sensitive predictor of bacterial infection compared to PCT and CRP, and different levels of IL-6 predict different extents of infection." (PMID 35463642, 2022). "However, higher IL-6 levels were not independently associated with early infection in this group." (PMID 36555941, 2022). "Similar to the mtDNA levels, the levels of PICs (IL-6, IL-1β, and TNF-α) and IL-10 were consistently downregulated in patients with OmicronS infection." (PMID 36230930, 2022). "We found that the expressions of pro-inflammatory cytokines such as IL-6, IL-1 β, IL-17, TNF-α, and TGF-β were significantly increased after an MP infection." (PMID 35383237, 2022). "Low HDL and ApoA-1 levels during the infection correlate with higher levels of inflammatory markers, such as C-reactive protein (CRP) and interleukin-6 (IL-6), and also correspond with higher mortality rates." (PMID 36140421, 2022). "The results show that the secretion levels of IL-1β and IL-6 from the BALF and serum of Nlrp6−/− mice were significantly lower than those of WT mice after infection, while the secretion levels of TNF-α did not change." (PMID 36224650, 2022).
infection (continued). "Indeed, several key antiviral effectors and inflammatory drivers remained upregulated at late infection time points in older mice when compared to the 10 w-old animals, including several that were poorly upregulated initially in the older cohort; these included Il6, Isg15, Cxcl10, and Ifit2." (PMID 36415465, 2022). "Some inflammatory cytokines, including IL-1β, IL-6, IL-8, and TNF-α, were frequently measured during biomaterial-related infections." (PMID 35203495, 2022). "Th cells, which are CD4+ T cells, play an important role in protecting the body from infection and secrete both proinflammatory cytokines (e.g., IFN-γ, TNF-α, and IL-6) and anti-inflammatory cytokines (e.g., IL-10)." (PMID 35001010, 2022). "Future experiments should examine the spatiotemporal expression and origins of IL-6 after UTI and how systemic increases correspond to brain levels across the entirety of infection." (PMID 36380004, 2022). "The expression of CD11b, CD4, CD14, and CD68 for M0; IL-6, HLA/DRA, and CXCL10 for M21, and IL-10, CD163, fibronectin-1 or FN1, and CCL17 was evaluated by qPCR at 2 and 24 h after infection." (PMID 35889103, 2022). "Mice in the CoHo-PBS group significantly reduced the mRNA expression levels of pro-inflammatory cytokines (IL-1β, IL-6, and TNF-α) compared with the SiHo-PBS group after infection." (PMID 35123452, 2022). "On the other hand, significant amounts of soluble IL-6 and IFN-β were detected in the supernatant from infected cells at 48 h after infection." (PMID 35215199, 2022). "The increase in IL-1α, IL-6, KC, MCP-1, G-CSF, and eotaxin was abolished in Trpm5–/– mice after infection." (PMID 35503420, 2022). "SAA production is regulated by IL-1, IL-6, and TNF, and SAA is released in response to infection and injury." (PMID 35449688, 2022). "Our findings demonstrated decreased expression and secretion of IL8, IL6 and TNFα, while CXCL5, PAI-1 and IFNα remained unaffected even 12 hours post-infection." (PMID 36389723, 2022). "Therefore, IL-6 may be both an indicator of acute inflammation, or undetected infection." (PMID 35277037, 2022). "In the acute phase of an infection, plasma levels of the inflammatory cytokines TNF-α, IL-1β and IL-6 increase, followed by enhanced secretion of acute-phase proteins that contribute to antimicrobial defence." (PMID 36510325, 2022). "We observed that SP600125 promoted the expression levels of IL-6, CCL21, IFN-β, MX, and OASL, but the expression level of IL-1β decreased in DEF cells in the presence of CHa strain infection." (PMID 35837399, 2022). "Current evidence suggests that the use of promising diagnostic markers like CD11b, CD64, IL-6, IL-8, PCT, and CRP, either alone or in combination, might be helpful when considering to discontinue antibiotics at 24–48 h of onset of the suspected infection process." (PMID 35345614, 2022). "Four strains with the highest viral copy numbers (n = 4) and three strains with the lowest viral copy numbers (n = 3) were selected to evaluate TNF-α, IL-6, IFN-β, ISG-15, IFITM1, and TRIM22 expression levels at 6 h post-infection." (PMID 36146585, 2022). "In this study, we observed that upon phagocytosis of L. corymbifera, human monocytes released IL-1β during the first hours of infection, while TNF-α and IL-6 were significantly released in later stages of the infection." (PMID 36311802, 2022). "IL-6 and TNF-α are inflammatory cytokines synthesized by many cell types such as monocytes, macrophages, and fibroblasts in response to infections, and play pivotal roles as signal molecules involved in various immune responses." (PMID 35167625, 2022). "Here, we report that cDC2 subtypes exhibit similar infection‐induced gene signatures, with the upregulation of IFN‐stimulated genes and IL‐6 signaling pathways." (PMID 34333764, 2022). "In a glioblastoma model, infection with CHIKV resulted in apoptosis and an increased expression of IL-1, TNF-α, IL-6, and CXCL9." (PMID 36016408, 2022).
infection (continued). "Next, we evaluated the presence of soluble polypeptides for IFNγ, IL-1β, IL-4, IL-6, IL-8, IL-10, CXCL10, and TNFα in serum of animals following infections with Att-S74-T3Bo and Vir-S74-T3Bo." (PMID 36466866, 2022). "Other pro-inflammatory cytokines such as IL-1β, IL-6, and TNF-α are regulators of host responses to infection and positive mediators of inflammation." (PMID 36320076, 2022). "Correspondingly, BCG ΔPPE36 infection led to the increased inflammatory cytokines (TNF-α, IL-6, and IL-1β) and the reduced lung bacterial loads." (PMID 35237255, 2022). "Remarkably, the knockdown of Nbeal2 significantly promoted the production of IL-1α, IP-10, IL-6, CCL-4 and TNF-α at 24 h post-infection in P815 cells infected with H1N1 virus and H5N1 virus." (PMID 35215885, 2022). "Previous data demonstrated that infection with attenuated IBV upregulated the expression of proinflammatory cytokines, including IL-1β, IL-6, and IFN-γ." (PMID 35392927, 2022). "Infection with MERS-CoV-MA-Δ4b and MERS-CoV-mNLS led to reduced levels of IFN-β and IL-6 compared to MERS-CoV-MA-WT at 4 and 6 dpi, suggesting that the nuclear localization of 4b was necessary in vivo to induce the expression of IFN-β and IL-6." (PMID 36129908, 2022). "During the latent and reactivation phase of MDV infection (7–28 dpi), the transcriptional upregulation of chicken IL-1β, IL6, IL-8L1, IFN-γ, and PML in the spleen and bursa induced by MDV/RB1B infection was overall stronger than that of MDV/CVI988." (PMID 36680047, 2022). "vaccination resulted in significantly lower levels of evaluated proinflammatory cytokines, including IL-6, IP10, IL-1β, MCP-1, and IFN-γ in the lungs of infected mice at day 4 after infection, presumably due to the substantially reduced virus replication." (PMID 35446790, 2022). "On contrary, secretion of IL-6, IL-8 and IL-18 was significantly higher in HIV/TB patients compared to patients with HIV and TB mono-infections." (PMID 35804458, 2022). "At 4 dpi, the expression of cytokines and chemokines G-CSF, IFN-γ, IL-6, KC, MCP-1, MIP-1α, MIP-1β, and RANTES in the brain of suckling mice was significantly upregulated after P9 infection (p < 0.05, or 0.01, 0.001)." (PMID 35755996, 2022). "While the SARS-CoV-2 single-infection group showed moderate increases of IL-1α (at 7 dpi), IL-6 (at 2, 5, 7 dpi), and IFN-β (2 dpi), their expression levels were lower than those of the IAV single-infection group." (PMID 35107382, 2022). "Influenza virus infection induced the release of inflammatory responses, with IL-6 and TNF-α levels in nasal irrigation fluid peaking early in the infection (day 2), and correlating directly with viral titers, temperature, mucus production, and symptom scores." (PMID 36034844, 2022). "As an inflammatory protein, CCL4 coordinates the immune response to infection or inflammation and promotes the expression of pro-inflammatory cytokines including TNF—α, IL-6 and IL-1 β in activated macrophages and fibroblasts during inflammation." (PMID 35287569, 2022). "Secondly, infection with SARS-COV-2 significantly increased the level of TNF-α and IL-6, suggesting that activated microglia lead to neuroinflammation." (PMID 36353605, 2022). "SARS-CoV-2 severe infection is characterized by the high expression and release of cytokines (such as TNF, IL-1, IL-6, IL-8) and a low expression of interferon-γ." (PMID 35741174, 2022). "Elevated pro-inflammatory cytokine levels were detected for WNV infection at 48- and 72-h post-infection, with key inflammatory cytokines IL-1β, TNF-α, IL-6 and IL-8 showing a statistically significant increase." (PMID 36297275, 2022). "The results manifest that the mRNA levels of pro-inflammatory cytokines (IL-1β, IL-6, and TNF-α) in the PBS group increased significantly after infection." (PMID 35123452, 2022). "Immunized mice showed an early, yet discrete, increase in IL-6 and TNF-α in BAL fluids, while the control group had a delayed response upon infection." (PMID 36477013, 2022).
infection (continued). "After 48 h of infection, the levels of TNF, CXCL8, IL6, CSF2, CD180, CD14, and CCL2 levels increased and those of IL-10, INFB1, and CXCL10 decreased." (PMID 36296238, 2022). "For example, neutrophil numbers in the lungs and IL-6 and IFN-γ levels were better predicted in the later days of infection, while viral load was more accurately predicted at the peak of infection." (PMID 36346236, 2022). "In contrast, the adjuvanted (VSA-1, QS-21) sCal vaccine groups showed lower levels of inflammatory cytokines (TNF-α, IL-6, IFN-γ, IL-1β) in the lung compared to the naïve mice with infection." (PMID 36146461, 2022). "Nonetheless, the normalization with GAPDH as a reference gene produced a high-NRF2–high-IL-6 expression phenotype as both IL-6 and NRF2 showed massive induction (>400-fold) in patients with mild infection and in pre- and post-CAM patients." (PMID 36377893, 2022). "Production of proinflammatory cytokines TNF-a and IL-6 in mice infected with ∆UDC20 mutant, was significantly higher than those of mice infected with wild-type strain SC84 at 8 h post-infection." (PMID 36031944, 2022). "The results showed a significant increase in both mRNA and protein levels of IL-6, IL-1β, and TNF-α in PBMCs and THP-1 cells after SFTSV infection." (PMID 36569095, 2022). "To further investigate this assumption, we downregulated αvβ3 integrin in SK-OV-3 cells using specific siRNA for the β3 integrin subunit, and subsequently determined the gene expression of IL-6, IL-8 and TNF-α following HAdV26 infection." (PMID 35458402, 2022). "The expression levels of inflammation-related genes, including IL-6, IL-12, IFN-β, and IL-1β, were also significantly increased after infection for 36 or 48 h." (PMID 35682869, 2022). "Based on recent studies, patients classified as having severe infection had elevated levels of LDH, IL-6, and leukocytes." (PMID 35572676, 2022). "Following unisexual infection, the gene expression of the Th1 cytokines IFN-γ, IL-1β, IL-6 was upregulated in both the male-infected and female-infected groups compared to naive mice." (PMID 36505463, 2022). "Many inflammatory cytokines including IFN-γ, IL-6, IL-10, IL-12, IL-18, TNF-α, and CXCL9 are elevated in patients with HLH, and the cytokine patterns are helpful in differentiating HLH from infections or other inflammatory entities." (PMID 35296096, 2022). "During infection, pro-inflammatory markers—C-reactive protein (CRP), interleukin-6 (IL-6) as well as interferon-gamma-inducible protein-10 (IP-10)—respond acutely." (PMID 35682203, 2022). "LPS stimulated IL-12, IL-17A, IL-1β, IL-6 and IL-8 were significantly higher post-infection than during antibiotic therapy, as well as Poly:IC stimulated IFN-γ, IL-1β and IL-6." (PMID 35360000, 2022). "IL-6: 9.8–fold increase vs HIV and 11.3-fold increase vs TB, p = 0.001; IL-8: twofold increase vs the group of patients with HIV mono-infection and 2.2-fold increase vs the TB group, p = 0.001." (PMID 35804458, 2022). "Our results indicate that the expression of IL6, IL12B, IL1R2, IL23R, IL12RB1 and IL12RB2 increased after DTMUV infection." (PMID 35585616, 2022). "All participants with chronic or active infections other than SARS-CoV-2, using medications targeting IL-6, or antibiotic use within one month of sample collection were also excluded." (PMID 35617421, 2022). "Simultaneously, the protein levels of the inflammatory factors, including IL-1β, IL-6, and IL-8, were upregulated comparing the ASFV-infected to uninfected with infection time." (PMID 36311798, 2022). "The mRNA levels of IL-1β, IL-6 and TNF-α were significantly higher in the brains and lungs of ISG15-/- mice as compared with those of WT mice at different time points post infection." (PMID 36315588, 2022). "In conclusion, to investigate infection in a military scenario, we develop a WMC-MDP for multiplexed detections of CRP, PCT, and IL-6." (PMID 35144683, 2022).